LCN2 (lipocalin 2)
Diseases named in the same sentence as LCN2 in open-access papers (continued):
Sharing a sentence is not in itself a finding about the gene and the disease.
colitis (continued). "Furthermore, increased secretion of Lcn2 stabilized MMP-9 via direct protein-protein interaction, which further aggravated the colitis." (PMID 24465207, 2014). "Specifically, fecal Lcn-2 was elevated by more than 10-fold in response to DSS concentrations that induced low-grade/sub-clinical inflammation and elevated by over 10,000-fold in response to DSS concentrations that induced histopathologically evident colitis." (PMID 22957064, 2012). "In contrast, the negative influence of TCDD in C. rodentium infection was not replicated in the DSS colitis model where TCDD treated mice exhibited less weight loss and the overall levels of Lipocalin-2 declined faster than in mice that had not received TCDD (Fig.EV1D–F)." (PMID 40502009, 2025). "We hypothesized that Hnf4aΔIEC mice reared in the absence of microbiota would not develop colitis, episodically elevated fecal Lcn2, or episodic loose stools." (PMID 37526424, 2023). "Additionally, reduced mRNA expression of Ncr1 —coding for NKp46, one of the NK triggering receptors— and a trend towards increased Lcn2 —coding for lipocalin-2, also named NGAL, a neutrophil secondary granule marker— in colons of Cd6-/- mice undergoing DSS-induced colitis was observed." (PMID 36211446, 2022). "On the other hand, CRP and Lcn-2 were not always altered between these different colitis models." (PMID 28566745, 2017). "While Lcn2 KO mice did not develop spontaneous colitis, a rapid onset and development of colitis was observed in Lcn2/IL-10 DKO mice soon after the weaning period compared to IL-10 KO mice, suggesting that the innate immune responses were disrupted in the colonic tissues of Lcn2/IL-10 DKO mice." (PMID 27734904, 2016). "Moreover, LCN2 is overexpressed in the intestine in colitis patients and acts as a negative prognostic indicator in colorectal cancer." (PMID 25940797, 2015). "Interestingly, mice lacking Lcn2 were considerably protected against S. Typhimurium-induced colitis even at the later stages of infection, confirming the key role of this secreted protein in S. Typhimurium pathogenesis." (PMID 24465207, 2014). "This novel mechanism by which S. Typhimurium exploits the host Lcn2 and MMP-9 synergy to aggravate inflammation and colitis severity is critical, as it calls for the reinterpretation of studies on microbial pathogenesis; other potential pathogens may also employ similar mechanisms." (PMID 24465207, 2014). "Together, these observations suggest that the mechanistic chain of events during S. Typhimurium infection in wild-type and Lcn2−/− mice was fundamentally similar; the absence of Lcn2 exclusively conferred protection to these mice against S. Typhimurium-induced colitis." (PMID 24465207, 2014). "Indeed, we used fecal Lcn-2 as a means to distinguish colitic and non-colitic toll-like receptor 5 (TLR5) deficient mice, thus enabling us to monitor the intestinal microbiota as colitis developed." (PMID 22957064, 2012). "Mice lacking LCN2 in ILC3s or administration of a p38 pathway inhibitor exhibited similar phenotypes of ILC3 and colitis to those observed in GPX4 conditional knock-out mice." (PMID 39300068, 2024). "Intriguingly, relative to the basal group, the colonic and serum Lcn2 was significantly elevated only in the Inu‐DSS group but not in the Con‐DSS group, further supporting our observation that inulin exacerbated DSS‐induced colitis." (PMID 37489647, 2023). "Whereas the current biomarkers, CRP and Lcn-2, did not discriminate between the DSS-induced and IL10−/− mouse models of colitis, our signature could make this distinction." (PMID 28566745, 2017). "To assess the role of Lcn2 in intestinal inflammation, we compared intestinal inflammation between IL-10 KO and Lcn2/IL-10 DKO mice, because Lcn2 KO mice did not develop spontaneous colitis." (PMID 27734904, 2016).
kidney injury (99 papers, 2007 to 2026). Trauma to the kidney. "Candidate genes and/or their proteins such as HAVCR1 (KIM-1) and LCN2 (NGAL) in body fluids were also associated with kidney injury." (PMID 34276651, 2021). "Lcn-2, also named neutrophil gelatinase associated lipocalin, is a recently identified marker for acute kidney injury as well as chronic kidney disease." (PMID 28860665, 2017). "LCN2 was originally considered a biomarker of acute kidney injury due to its function in capturing bacterial siderophores." (PMID 35470375, 2022). "Further, we studied hypoxic cellular stress response protein Lcn2 (NGAL), a sensitive marker for acute kidney injury." (PMID 32849588, 2020). "We recently described lipocalin-2 (Lcn-2) as a potent determent of MΦ polarization in the context of kidney injury." (PMID 32188161, 2020). "In conclusion, we show that both the cellular source, namely TEC or MΦ, as well as its iron-load define the biological function of Lcn-2 in CLP-induced kidney injury." (PMID 33065981, 2020). "The Lcn2-reporter mouse has been shown to be a significantly more sensitive system to test the time course of kidney injury than sCr or BUN15." (PMID 31508501, 2019). "Previous studies also indicated that the urinary LCN2 can be separated into several isoforms in animal models of drug-induced kidney injury and in mice with diabetic nephropathy or ischemia-reperfusion injuries." (PMID 26949374, 2016). "Lcn2 has been proposed as biomarker for acute kidney injury based on its quaternary structure." (PMID 40582410, 2025). "Moreover, an increase in inflammatory (TNF-α and TGF-β) and apoptotic (caspace-3) markers, an elevation in gene-based kidney injuries markers (Kim-1 and lipocalin-2), and pathological tissue changes were determined." (PMID 39837868, 2025). "Lipokine 2 (LCN2), also known as neutrophil gelatinase-associated lipocalin (NGAL), which has been suggested as a biomarker of kidney injury, regulates innate immunity such as neutrophil recruitment, and it has also been reported to be associated with various lung diseases and infections." (PMID 39107780, 2024). "Furthermore, recurrent regulation of e.g. Havcr1 (KIM-1) and Lcn2 (NGAL) were found, indicating induced kidney injury at these absorbed doses (up to 140 MBq of injected activity)." (PMID 26287527, 2015). "Interestingly, some of the drivers for group separation (i.e., Tnfa, Ccl2, Il6, Lcn2, and UACR) were not significantly different between any of the four mouse groups when analyzed in isolation, but are widely known indicators of kidney injury." (PMID 34835482, 2021).
Hypertension (79 papers, 2011 to 2026). The presence of chronic increased pressure in the systemic arterial system. "Lipocalin-2 causes vascular inflammation, endothelial dysfunction, and finally hypertension by promoting oxidative stress and inflammatory reaction." (PMID 29731737, 2018). "Serum and WAT concentration of lipocalin-2 had been found increased markedly in dietary and genetically obese animals with hypertension, whereas the obese mice deficient of lipocalin-2 exhibited significantly lower blood pressure." (PMID 29731737, 2018). "Meanwhile, the association between single-nucleotide polymorphisms in the gene encoding lipocalin-2 in humans also revealed a causal relationship between lipocalin-2 and development of hypertension." (PMID 29731737, 2018). "Proportional correlations of CKD duration-PAI1 levels and sCr-lipocalin 2 levels but inverse correlations of orosomucoid 1-hypertension duration and SDMA-DBP were evident in cases." (PMID 41596619, 2026). "Particularly, alleviated circulating lipocalin-2 and its accumulation in aortae, and then vascular derangement and arterial hypertension was thus reversed." (PMID 29731737, 2018). "Moreover, the accumulation of lipocalin-2 protein in aortae of dietary obese mice with hypertension is also proved to be augmented significantly." (PMID 29731737, 2018). "Using a multiple logistic regression model, independent significant risk factors for subclinical atherosclerosis were identified, including age, sex, BMI, smoking status, FPG, fasting insulin, presence of hypertension, presence of dyslipidemia and lipocalin-2 or RBP4." (PMID 23799122, 2013). "In addition, lipocalin-2 serum levels were higher in patients suffering from hypertension and were reported to possibly decline in type 2 diabetes patients, indicating a complex interplay between metabolic diseases and serum lipocalin-2 levels." (PMID 37189804, 2023). "Participants with hypertensions had increased circulating myoglobin (p = 0.02) and LCN2/NGAL (p = 0.02), but no changes in VCAM-1 (p = 0.15) or platelets (p = 0.30)." (PMID 37598150, 2023).
Stroke (79 papers, 2012 to 2025). Sudden impairment of blood flow to a part of the brain due to occlusion or rupture of an artery to the brain. "The Lcn2 gene [encoding for lipocalin-2 (LCN2)] showed the trend of upregulation at 1 and 5 days in post-stroke ChP where the p-value was close to 0.05 (p = 0.0585)." (PMID 38107410, 2023). "Previous studies with small sample sizes showed that LCN-2 was implicated in stroke in patients with renal dysfunction." (PMID 37155257, 2023). "Our previous study found that the accumulation of deamidated lipocalin-2 in arteries caused vascular inflammation and endothelial dysfunction, which are key processes in the development of stroke." (PMID 37155257, 2023). "The use of B2M, cystatin C and LCN-2 as possible biomarkers allows the early identification of people with high stroke risk." (PMID 37155257, 2023). "We aimed to investigate the relationship of B2M, cystatin C, and LCN-2 with stroke risk in a general Chinese population." (PMID 37155257, 2023). "The mechanisms underlying the association between LCN2 and neurological deterioration after stroke are incompletely clear." (PMID 36974345, 2023). "Serum B2M, cystatin C and LCN-2 are significantly associated with stroke risk and are potential novel clinical biomarkers in the assessment of stroke risk." (PMID 37155257, 2023). "Significantly elevated LCN2 in cerebrospinal fluid (CSF) or peripheral blood is associated with poor functional prognosis after stroke." (PMID 37543589, 2023). "Lastly, in assessing cellular factors which possibly cause stroke-mediated ChP damage, we identified a gene and protein upregulation in LCN2, a critical component of the ensuing inflammatory response." (PMID 38107410, 2023). "Lipocalin-2 (LCN-2) is a neutrophil gelatinase-associated protein that influences diverse cellular processes during a stroke." (PMID 35493318, 2022). "As a result, future research should focus on the mechanisms underlying LCN2’s beneficial and harmful effects in the context of stroke and brain injury." (PMID 36187347, 2022). "An association between increased LCN2 protein expression and stroke-induced loss of GRP78 protein in neurons was also observed." (PMID 35440572, 2022). "Neutrophil elastase and lipocalin-2 are two critical inflammatory mediators linked to neurovascular injury in stroke." (PMID 32973660, 2020). "In ischemic stroke patients, higher plasma levels of LCN2 were associated with a worse clinical outcome at 90 days and with the occurrence of post-stroke infections." (PMID 27152948, 2016). "Increased levels of LCN2 were associated with post-stroke infections and supposedly reflect the response of circulating neutrophils to infections." (PMID 27152948, 2016). "LCN2 can significantly exacerbate myelin loss in mice with MS, spinal cord injury, and stroke." (PMID 41007258, 2025). "Although research on the role of B2M in ocular diseases is limited, neuroscience suggests that both B2M and LCN2 may serve as key biomarkers for assessing stroke risk and prognosis." (PMID 40083945, 2025). "Moreover, elevated LCN2 levels were found to be associated with poor survival in several diseases, including cancer and stroke." (PMID 38704585, 2024). "LCN2 is a secreted protein (neutrophils, hepatocytes, and renal tubular cells mainly secrete LCN2) of the lipocalin family implicated in the development of several diseases, including cancer, cardiovascular disease, and stroke." (PMID 37240031, 2023). "Knowing that LCN2 signaling damages both neurons and the blood-brain barrier, LCN2 expression in brain tissue and in circulation after harmful conditions may be the direct cause of the brain injury that follows a stroke." (PMID 38107410, 2023). "After stroke, an increase in serum LCN2 is not only caused by kidney injury, but may also originate in the CNS." (PMID 37543589, 2023).
Stroke (continued). "However, Lcn2 gene deficiency significantly improved post-stroke sensorimotor function compared with the WT group (P < 0.001 for days 1, 3 and 7; P = 0.007 for day 14; P = 0.014 for day 28)." (PMID 37353794, 2023). "However, the underlying mechanism and signaling pathways of LCN2 in stroke are complicated and ambiguous." (PMID 36187347, 2022). "To test our hypothesis that increased LCN2 expression in RA causes adjacent neuron degeneration in wild-type stroke brains, we first evaluated the effect of recombinant LCN2 (Re-LCN2) protein on neuronal viability and degeneration in cultures." (PMID 35440572, 2022). "This review focuses on the mechanisms based on previous studies published online, discusses the role of LCN2 in brain injury after stroke, summarizes the underlying pathological progress, and provides a comprehensive introduction to the clinical intervention-based study." (PMID 36187347, 2022). "In the context of stroke, both hypoxia itself and the release of danger- associated molecular pattern molecules (DAMPs) following reperfusion are potential candidates to stimulate LCN2 expression." (PMID 30871254, 2019). "Furthermore, LCN2 is implicated in several CNS diseases, including stroke and AD." (PMID 41007258, 2025). "Plasma level of LCN2 was found to be significantly elevated in patients with ischemic stroke, especially in the early stages, and to be a risk factor for unfavorable modified Rankin scale scores, the occurrence of post-stroke infections and cardiovascular mortality." (PMID 34179014, 2021). "In addition, aspirin may be helpful in reducing the inflammation associated with stroke by targeting pro-inflammatory proteins described in this study, such as lipocalin-2, IP-10 and SAA or by targeting and promoting anti-inflammatory proteins such as IL-13." (PMID 33930055, 2021). "At the same time, HBB levels stayed high, although PSA samples from stroke patients showed significantly lower levels of LCN2, LAIR2, and RPS10." (PMID 40270596, 2025). "Specifically, PPARα KO led to increased expression levels of Gadd45b, Nppa, Hdc, Lcn2, Il6, Sox4, Marcksl1, Saa3, Ucn2, Met, Dusp10, Elovl7, Ngf, C3, Il11, Hmox1, Alox5, Tnfsf9, Angptl4, Plin2, H19, Csf2rb, Atf3, and Col7a1 following stroke." (PMID 40362325, 2025). "Improved blood–brain barrier leakage and attenuated post-stroke LCN2 induction were observed in stroke-reperfusion-injured mice following specific neutralization of LCN2 with a monoclonal antibody." (PMID 41007258, 2025). "Subsequent mechanistic investigations in Lcn2-null murine stroke models demonstrated attenuated manifestations of BBB compromise, neurological dysfunction severity, cerebral infarct volume, and neutrophilic infiltration." (PMID 40307216, 2025). "Reactive astrocytes are reported to use NOX signaling to stimulate Lcn2 expression and secretion, and blocking astrocytic NHE1 activity promotes the reduction of Lcn2-mediated neurotoxicity after stroke." (PMID 37672148, 2024). "It has also been reported that reactive astrocytes secrete the lipocalin-2 (LCN2) glycoprotein to regulate cellular processes such as inflammation and injury in neurons after stroke." (PMID 37728588, 2024). "In stroke patients and animal models, LCN2 is significantly elevated, proven to be related to neuroinflammation and cell death, and used as a biomarker for brain injury." (PMID 37728588, 2024). "considered that high levels of Lcn-2 can function as a “help-me” signal, which makes glial cells more protective by altering their phenotype that protects neurons in stroke and cerebral ischemia models." (PMID 38533497, 2024). "Previous studies have indicated that Lipocalin-2 (Lcn-2) is overexpressed and assumes a crucial role in various pathological conditions related to neuroinflammation, including brain injury, stroke, AD and others." (PMID 38533497, 2024).